DACH1 (dachshund family transcription factor 1)
Diseases named in the same sentence as DACH1 in open-access papers (continued):
Sharing a sentence is not in itself a finding about the gene and the disease.
hepatocellular carcinoma (10 papers, 2014 to 2023). A malignant tumor that arises from hepatocytes. "Loss of DACH1 expression was found in breast, prostate, lung, endometrial, colorectal and hepatocellular carcinoma." (PMID 24743895, 2014). "Meanwhile, restoration of DACH1 expression sensitizes gastric and colorectal cancer cells to docetaxel and enhances chemosensitivity to 5-fluorouracil (5-FU) in hepatocellular carcinoma." (PMID 27203207, 2016). "The expression of DACH1 was reduced in breast, prostate, lung, endometrial, colorectal and hepatocellular carcinoma, but it was increased in ovarian cancer." (PMID 24743895, 2014). "DACH1 expression was regulated by promoter region hypermethylation in human colorectal and hepatocellular carcinoma." (PMID 24743895, 2014). "DACH1 is epigenetically silenced in colorectal and hepatocellular carcinoma." (PMID 27993161, 2016). "The binding of EYA2 and DACH1 transcriptionally regulates the expression of SOCS3 and inhibits the progression of hepatocellular carcinoma by blocking the activation of the SOCS3-mediated JAK/STAT signaling pathway." (PMID 36750914, 2023). "Our previous study found that DACH1 performed anti-proliferation effect by activating TGF-β signaling and inhibiting c-Myc expression in human hepatocellular carcinoma cell lines." (PMID 24743895, 2014).
ovarian carcinoma (10 papers, 2012 to 2023). A malignant neoplasm originating from the surface ovarian epithelium. "Other transcripts that were upregulated during ovarian cancer spheroids formation include DACH1, the Discoidin domain receptor (DDR1), the winged helix transcription factor Forkhead box P1 (FOXP1), and MUC1." (PMID 37189618, 2023). "For example, DACH1 protein levels were increased with the invasiveness of the ovarian cancer and subcellular distribution of DACH1 changed from nucleus in normal tissue to cytoplasm in cancer." (PMID 32550045, 2020). "The expression of DACH1 has been reported to be reduced in different types of cancers, but increased in ovarian cancer." (PMID 24912879, 2014). "While the role of DACH2 in human tumourigenesis remains unexplored, alterations of DACH1 expression has been described in several cancer forms, e.g. breast, prostate, endometrial, gastric and ovarian cancer." (PMID 22284433, 2012). "DACH1 was up-regulated in ovarian cancer, which might facilitate the resistance to the TGF-β signaling pathway." (PMID 36750914, 2023). "Moreover, DACH1 protein levels were increased with the invasiveness of ovarian cancer and the subcellular distribution of DACH1 changed from nucleus in normal tissue to cytoplasm in cancer." (PMID 36750914, 2023). "Moreover, DACH1 localization shifts from the nucleus in normal tissue to the cytoplasm in ovarian cancer." (PMID 27442438, 2016). "Furthermore, it has also recently been reported that over-expression of DACH1 protein is associated with poor prognosis when expressed in the cytoplasm rather than nuclei of ovarian cancer cells indicating disease progression, compatible with loss of TSG function." (PMID 24392136, 2014). "However, DACH1 is up-regulated in myeloid leukemia via interaction with HOXA9 and overexpression in ovarian cancer with poor prognosis as promotion sensitivity gene." (PMID 30261897, 2018).
gastric cancer (8 papers, 2014 to 2021). A primary or metastatic malignant neoplasm involving the stomach. "DACH1 proteins contain a domain conserved with the proto-oncogenes Ski and Sno, and DACH1 suppresses gastric cancer cell proliferation by inhibiting TGF-β signal pathway activity through binding Smad445." (PMID 28387750, 2017). "Intriguingly, 5-Aza-2′-deoxycytidine (decitabine), a potent demethylating agent, reactivates DACH1 in gastric cancer, suggesting that low-dose decitabine combined with traditional chemotherapy may improve the efficiency of treatments against tumors in which DACH1 expression is silenced." (PMID 27203207, 2016). "DACH1 may also antagonize EMT in part by inactivating Wnt/β-catenin signaling; indeed, DACH1 was recently found to downregulate β-catenin in hepatocellular and gastric cancer." (PMID 27203207, 2016).
esophageal cancer (6 papers, 2014 to 2023). A primary or metastatic malignant neoplasm involving the esophagus. "Both in vivo and in vitro studies have demonstrated that DACH1 suppresses human esophageal cancer growth by activating TGF-β signaling." (PMID 27110300, 2016). "Above results indicate that DACH1 methylation is an early event of esophageal carcinogenesis and methylation of DACH1 is accumulated during progression of esophageal cancer." (PMID 24743895, 2014). "It suggests that DACH1 suppresses cell proliferation by inhibiting G1/S checkpoint in esophageal cancer." (PMID 24743895, 2014). "We found that DACH1 expression was regulated by promoter region hypermethylation in esophageal cancer cell lines." (PMID 24743895, 2014). "The expression of DACH1 was evaluated by immunohistochemistry (IHC) in 30 cases of matched esophageal cancer and adjacent tissue samples." (PMID 24743895, 2014). "In conclusion, DACH1 is frequently methylated in human esophageal cancer and methylation of DACH1 is involved in the early stage of esophageal carcinogenesis." (PMID 24743895, 2014). "DACH1 expression was regulated by promoter region hypermethylation in esophageal cancer." (PMID 27110300, 2016). "DACH1 suppresses esophageal cancer growth by activating TGF-β signaling." (PMID 24743895, 2014). "The function of DACH1 on esophageal cancer was also studied in xenograft mice model." (PMID 24743895, 2014). "DACH1 suppressed human esophageal cancer cell tumor growth in xenograft mice." (PMID 24743895, 2014). "It suggest that DACH1 is a possible tumor suppressor in esophageal cancer." (PMID 24743895, 2014). "Furthermore, a recent study indicated that DACH1 methylation might be an early marker in esophageal cancer and correlated with progression." (PMID 36750914, 2023). "Therefore, restoration of DACH1 by demethylase may be a promising therapeutic target for patients with esophageal cancer." (PMID 36750914, 2023).
glioma (6 papers, 2014 to 2024). A benign or malignant brain and spinal cord tumor that arises from glial cells (astrocytes, oligodendrocytes, ependymal cells). "This study constructs a risk model that can predict glioma susceptibility to temozolomide and validates the function of the feature gene DACH1, which provides a promising target for the research of temozolomide resistance." (PMID 36959804, 2023). "Interestingly, the induction of the expression of DACH1 decreased cell proliferation in a series of glioma cell lines, whereas loss of DACH1 increased the number of tumor-initiating cells through transcriptional activation of bFGF." (PMID 26337424, 2016). "Previous studies have shown that FGF2 expression was transcriptionally suppressed by Dach1 in glioma cells and on the contrary, FGF2 was shown to activate DACH1 during skeletal development in mouse." (PMID 38581619, 2024). "PCR and western blot were performed to determine the difference in expression of the feature gene DACH1 between glioma cells and temozolomide-resistant glioma cells." (PMID 36959804, 2023). "This study builds and verifies a risk model for temozolomide-treated patients to predict their prognosis and explores the function of one of the feature genes, DACH1, in gliomas." (PMID 36959804, 2023). "The methylation of SFRP1, SFRP2, PPP2R2B, DKK1, SOX17, and DACH1 was analyzed in 64 glioma samples using methylation-specific polymerase chain reaction (MSP)." (PMID 26337424, 2016). "The results show that as the glioma grade increases, DACH1 expression decreases." (PMID 36959804, 2023). "Thus, DACH1 very likely regulates glioma temozolomide resistance through transcriptional misregulation in cancer." (PMID 36959804, 2023). "Therefore, DACH1 probably regulates these pathways to contribute to temozolomide resistance in glioma." (PMID 36959804, 2023). "Based on four signature genes (AHR, DACH1, MGMT, and YAP1), a risk model for predicting glioma sensitivity to temozolomide was constructed, and the results of timeROC in both the training and validation sets showed that the model had good predictive performance." (PMID 36959804, 2023). "However, in glioma, Dach1 has been shown to transcriptionally suppress FGF2 expression." (PMID 38581619, 2024). "In contrast to DACH1, epigenetic changes were reported to play a role in reducing DKK1 expression in gliomas." (PMID 26337424, 2016). "Beside the genes, which were described earlier as possible targets of epigenetic silencing in gliomas (SFRP1, SFRP2, DKK1), the methylation of PPP2R2B, SOX17, and DACH1 was also assessed." (PMID 26337424, 2016). "We also show that DACH1 and DKK1 methylation is an infrequent event in glioma." (PMID 26337424, 2016).
lymph node metastasis (5 papers, 2014 to 2021). "DACH1 was mainly found in the nucleus, and its expression was associated with several clinical parameters, including smoking, drinking, T classification, lymph node metastases, primary location and clinical stage in LSCC paraffin specimens." (PMID 30261897, 2018). "DACH1 methylation is associated with late tumour stage and lymph node metastasis." (PMID 24912879, 2014). "In our study, methylation of DACH1 was associated with late tumour stage and lymph node metastasis." (PMID 24912879, 2014). "DACH1 methylation is associated with higher tumour stage and lymph node metastasis." (PMID 24912879, 2014). "Here, our results presented that DACH1 expression was downregulated in the SCLC patients with lymph node metastasis." (PMID 30364292, 2018). "In addition, tumor tissues with lymph node metastasis (N1) had much less DACH1 than those without metastasis (N0)." (PMID 25788272, 2015). "Here, 186 upregulated (e.g., GSR, HCP5) and 144 downregulated DEGs (e.g., MET, GRM8, and DACH1) were identified between the SCLC patients with lymph node metastasis and without lymph node metastasis." (PMID 30364292, 2018).
pancreatic cancer (4 papers, 2015 to 2023). "In our study, we identified three tumor suppressor genes, DACH1, PCDH10 and SMAD4 as targets of miR-552 in pancreatic cancer." (PMID 33867818, 2021). "This upregulation of miR-552 induced by FOXM1 further inhibited the expression of three downstream targets DACH1, PCDH10, SMAD4, which are known as tumor suppressors in pancreatic cancer progression." (PMID 33867818, 2021).
renal carcinoma (4 papers, 2014 to 2025). A carcinoma arising from the epithelium of the renal parenchyma or the renal pelvis. "RNA protection assay and northern blot indicated that DACH1 was richly expressed in embryonal kidney cells and adult kidney tissues, but dramatically decreased in two renal cancer cells." (PMID 25322986, 2014). "The current study was conducted to analyze the DACH1 expression in relation to clinic-pathological characteristics and identify molecular targets of DACH1 in renal cancers." (PMID 25322986, 2014). "Expression of DACH1 was significantly decreased in human renal carcinoma tissue and was inversely correlated with proliferation, tumor grade, and TNM stage." (PMID 25322986, 2014). "The mRNA profiles GSE14994 consisting of 70 patients with renal cancers showed that DACH1 and PCNA were inversely correlated (p < 0.002)." (PMID 25322986, 2014). "In vitro proliferation, apoptosis and in vivo tumor growth were evaluated on human renal cancer cell lines with decitabine treatment or ectopic expression of DACH1." (PMID 25322986, 2014). "Although RCC originates from the tubule of kidney, DACH1 expression was markedly decreased in all 3 major types of renal cancers, including clear cell renal carcinoma and granular cell carcinoma." (PMID 25322986, 2014). "Expression of DACH1 was significantly decreased in human renal carcinoma tissue." (PMID 25322986, 2014). "Our results indicated that DACH1 attributed to the malignant behavior of renal cancer cells." (PMID 25322986, 2014). "However, there were no experimental evidence and detailed clinic studies to examine the role of DACH1 in renal cancer initiation and progression." (PMID 25322986, 2014). "Epigenetic silencing of DACH1 mRNA was also observed in renal cancer tissues." (PMID 25322986, 2014). "Therefore, we conclude that the lost expression of DACH1 led to higher cellular proliferation in renal cancer tissues." (PMID 25322986, 2014). "Our previous study also demonstrated that DACH1 inhibited cyclin D1 expression and inversely correlated with PCNA in renal cancer cells or blocked cell proliferation through a c-Jun DNA-binding partner." (PMID 27888806, 2016). "Our results indicated that DACH1 was a novel molecular marker of RCC and it attributed to the malignant behavior of renal cancer cells." (PMID 25322986, 2014). "Importantly, co-expression analysis demonstrated reverse relationship between protein expression of DACH1 and PCNA in renal cancer tissues." (PMID 25322986, 2014).
adenoma (3 papers, 2014 to 2025). A neoplasm arising from the epithelium. "As for the cancers, three different staining patterns emerged: marked and ubiquitous DACH1 expression resembling that seen in adenomas; complete loss of expression throughout the lesion; and patches of variable-intensity staining interspersed with areas of absent expression." (PMID 24472434, 2014). "Normal mucosa, adenoma, and carcinoma tissues obtained from the same patient were used to detect the expression of DACH1 and DNMT1 during CRC progression by IHC." (PMID 40370966, 2025). "In normal tissues, DACH1 was predominantly localized in the nuclei of epithelial cells, showing strong staining intensity, whereas moderate staining was detected in adenoma tissues, and weak or negligible nuclear staining was evident in adenocarcinoma tissues." (PMID 40370966, 2025). "DACH1 was recognized as a tumor suppressor gene in our study, supported by a significant decrease in DACH1 protein and mRNA expression from normal mucosa to adenomas and adenocarcinomas." (PMID 40370966, 2025). "A progressive decrease in DACH1 expression from normal mucosa to adenoma to adenocarcinoma were observed, while DNMT1 expression showed a corresponding increase, demonstrating an inverse relationship in both protein and mRNA levels." (PMID 40370966, 2025). "Based on BSP analysis, detailed methylation profiling across the normal mucosa-adenoma-adenocarcinoma sequence revealed that most CpG sites within the DACH1 promoter were unmethylated in normal mucosa." (PMID 40370966, 2025). "Half-quantification of IHC staining scores revealed a significant decline in the number of cases with high DACH1 expression (+++) across the “normal-adenoma-adenocarcinoma” progression, with its level being negligible in the adenocarcinoma group." (PMID 40370966, 2025). "Normal mucosa exhibited the highest levels of DACH1 expression, which was markedly reduced in adenoma and further diminished in carcinoma tissues." (PMID 40370966, 2025). "A progressive reduction in DACH1 expression was observed from normal colorectal mucosa to adenoma and adenocarcinoma tissues." (PMID 40370966, 2025). "DACH1 protein expression was found to decrease progressively from normal to adenoma to carcinoma tissues." (PMID 40370966, 2025). "The progressive increase in DNMT1 expression drives the epigenetic silencing of DACH1 via promoter methylation, facilitating the transition from adenoma to carcinoma." (PMID 40370966, 2025). "We demonstrated that DACH1 expression progressively decreased from normal colorectal mucosa to adenoma and adenocarcinoma tissues, while its methylation level and DNMT1 expression exhibited the opposite trend." (PMID 40370966, 2025). "Additionally, the relative mRNA expression of DACH1 followed a similar trend, with the highest levels observed in normal tissues, followed by a significant decrease in adenoma and the lowest levels in adenocarcinoma tissues." (PMID 40370966, 2025). "Consistently, in our case, DACH1 protein expression was upregulated in the COAD and READ and was highly enriched in stem cell-related GO terms, indicating DACH1 might maintain the stemness of crypt base cells and promote normal epithelium-adenoma-carcinoma progression." (PMID 34094897, 2021). "As such, our study systematically analyzed the expression patterns of DACH1 and DNMT1 across normal tissues, adenomas, and adenocarcinomas by integrating clinical samples with data from the TCGA database." (PMID 40370966, 2025). "A progressive decrease in DACH1 expression and a concomitant increase in DACH1 promoter methylation and DNMT1 expression were observed from normal mucosa to adenoma and adenocarcinoma tissues." (PMID 40370966, 2025).
chronic kidney disease (3 papers, 2016 to 2023). Impairment of the renal function secondary to chronic kidney damage persisting for three or more months. "In the last several years studies have demonstrated that DACH1 expression level is associated with incident chronic kidney diseases and provides a means to estimate glomerular filtration rate (eGFR)." (PMID 27888806, 2016). "We postulated that DACH1 expression may be altered in chronic kidney diseases and its function may be associated with the prognosis of renal diseases." (PMID 27888806, 2016). "In humans, DACH1 germline mutations have been shown to contribute to bilateral cystic renal dysplasia, chronic kidney disease (CKD), familial young-onset diabetes, pre-diabetes and cardiovascular diseases like coronary heart disease (CHD) and coronary arteriosclerosis." (PMID 27203207, 2016).
colorectal adenoma (3 papers, 2014 to 2025). An adenoma that arises from the colon or rectum. "Forty cases of each type, including normal colorectal mucosa, colorectal adenoma, and colorectal adenocarcinoma tissues, were collected for analysis of DACH1 levels." (PMID 40370966, 2025). "One of these, DACH1, consistently displayed marked upregulation in the colorectal adenomas we examined, and it was subjected to further investigation in a series of neoplasms representing different types and stages of colorectal tumor progression." (PMID 24472434, 2014). "Notably, six DE-TFs, DACH1, GTF2IRD1, MEIS2, NR3C2, SOX9, and SPIB, were identified as having a dynamic signature along the colorectal adenoma-carcinoma sequence." (PMID 34094897, 2021).
Diabetes (3 papers, 2014 to 2023). "In the Wellcome Trust Case Control Consortium, Diabetes Genetics Initiative and a recent Chinese GWAS, DACH1 was among the list of genes with nominal association (P<0.05) with T2D." (PMID 24465431, 2014). "In kidney tissue, the expression of DDX17 was also decreased in the Woroniecka Diabetes Glom database, which was in line with the DACH1 and TCF21 expression." (PMID 36875100, 2023). "Additionally, DACH1 suppresses pancreatic cell proliferation and is involved in diabetes insulin signaling." (PMID 37766305, 2023).